CDK4 (cyclin dependent kinase 4)
Diseases named in the same sentence as CDK4 in open-access papers (continued):
Sharing a sentence is not in itself a finding about the gene and the disease.
lipoma (24 papers, 2000 to 2025). A benign, usually painless, well-circumscribed lipomatous tumor composed of adipose tissue. "The medians for relative CDK4 expression were 0.9 (range, 0.3–8.0) for lipoma and 1.4 (range, 0.3–12.8) for ALT/WDL." (PMID 24965044, 2014). "The medians for CDK4 relative expression levels were 1.0 (range, 0.1–19.9) for lipoma and 2.9 (range, 0.4–22.4) for ALT/WDL." (PMID 24965044, 2014). "In whole tissue sections, the medians for MDM2 and CDK4 expression in ALT/WDL were higher than those in the lipomas (P < 0.05)." (PMID 24965044, 2014). "Both MDM2 and CDK4 relative expression levels in ALT/WDL were higher than those in lipoma (P < 0.05, Mann–Whitney U test)." (PMID 24965044, 2014). "In this study, we used whole tissue sections from surgically resected specimens to retrospectively analyze cytogenetic findings by quantifying MDM2 and CDK4 expression levels in lipomas and ALT/WDL with real-time polymerase chain reaction (PCR) from total RNA." (PMID 24965044, 2014). "The relative gene expression levels of MDM2 and CDK4 were studied in 38/168 samples (28 lipoma samples and 10 ALT/WDL samples) from core-needle biopsy sections." (PMID 24965044, 2014). "We evaluated the clinical utility of measuring MDM2 and CDK4 expression levels to establish a diagnosis of adipocytic tumors, with the aim of making a distinction between lipoma and ALT/WDL." (PMID 24965044, 2014). "Relative MDM2 and CDK4 expression levels in lipoma and ALT/WDL cases with a ring and/or giant chromosome were higher than those with 12q13-15 rearrangements and other abnormal karyotypes (P < 0.05, Steel-Dwass test)." (PMID 24965044, 2014). "The gene expression levels of MDM2 and CDK4 were studied in 149/168 whole tissue sections (108 lipoma samples and 41 samples from the 38 cases of ALT/WDL)." (PMID 24965044, 2014). "The safest discrimination between an ALT and a lipoma can be achieved by immunohistochemistry against the proteins of the MDM2 and CDK4 genes." (PMID 35626435, 2022). "More importantly, MDM2 and CDK4 nuclear positivity, especially MDM2 gene amplification, can be invaluable in distinguishing WDL from lipoma and inflammatory lesions." (PMID 36059611, 2022). "A series of lipoma (n = 124) and ALT/WDL (n = 44) cases were analyzed for cytogenetic analysis and lipoma fusion genes, as well as for MDM2 and CDK4 expression by real-time PCR." (PMID 24965044, 2014). "Moreover, the expression of MDM2 and CDK4 in whole tissue sections was compared with that in core-needle biopsy sections of the same tumor in order to determine whether real-time PCR could be used to distinguish ALT/WDL from lipoma at the preoperative stage." (PMID 24965044, 2014). "In this study, MDM2 and CDK4 expression levels, as determined by real-time PCR, were higher in ALT/WDL than in lipoma samples in whole tissue sections (P < 0.05)." (PMID 24965044, 2014). "All lipomas displayed a null MDM2/CDK4 phenotype, whereas all LL-WDL showed MDM2/CDK4 or CDK4 phenotypes." (PMID 10755400, 2000). "As per the definition, MDM2 amplification was significantly more common in ALTs (p < 0.01), although one ALT was negative, requiring additional cyclin-dependent kinase 4 (CDK4) testing to differentiate it from a lipoma in this specific case." (PMID 40564858, 2025). "Therefore, genes known to be related to lipomas were also considered as potential candidate genes, and included SPRYD7, LHFPL6, RCBTB2, RCBTB1, and CDK4." (PMID 39719593, 2024). "Thus, FISH testing of MDM2 and CDK4 gene amplifications provides greater accuracy in the diagnosis of ALT/WDLS and is considered the gold standard for differentiating it from a lipoma." (PMID 38132190, 2023). "The staining for MDM2 (MDM2 proto-oncogene) and CDK4 (cyclin-dependent kinase 4) was negative, therefore the lesion was diagnosed as a lipoma." (PMID 25890295, 2015).
lipoma (continued). "The gene copy number (mean levels) of lipoma was 0.8 and 0.9 for MDM2 and CDK4, respectively." (PMID 25176350, 2014). "Amplification of the 12q13-15 region has not been observed in lipoma, and the MDM2 and CDK4 proteins are known to be overexpressed in ALT/WDL but not in lipoma." (PMID 24965044, 2014). "Immunohistochemistry may be of help since markers such as MDM2 and CDK4, commonly evaluated in soft tissue tumors, are typically negative in lipoma cases." (PMID 40729232, 2025). "Spindel cell lipomas consist of bland spindle cells and are positive for CD34 and negative for MDM2 and CDK4." (PMID 40777097, 2024). "On the other hand, WDLS and DDLS were variably positive for CDK4 and MDM2, presenting a sharp contrast to MLS with or without lipoma-like components." (PMID 25650275, 2015). "Conversely, ring/giant marker chromosomes as well as immunohistochemical expressions of CDK4 and MDM2 characteristic of ALT/WDLS were never found in any case of MLS with a lipoma-like component." (PMID 25650275, 2015). "In MLSLC, the tumor cells were uniformly negative for CDK4 and MDM2 in both lipoma-like and myxoid areas." (PMID 25650275, 2015). "Moreover, we compared the results of MDM2 and CDK4 expression in whole tissue sections with those in core-needle biopsy sections in order to investigate whether real-time PCR for MDM2 and CDK4 could be used to distinguish between ALT/WDL and lipoma prior to surgery." (PMID 24965044, 2014).
anemia (23 papers, 2017 to 2025). A reduction in the number of red blood cells, the amount of hemoglobin, and/or the volume of packed red blood cells. "Embryos of Cdk6 or Cdk4 knock out mice died at the late stage of embryonic development because of the hematopoietic-deficiency caused anemia." (PMID 32047552, 2020). "The second most frequent side effect reported in these trials was anemia in the continuation of the CDK4/6i arms, ranging from 1.7 to 11%." (PMID 39677112, 2024). "In contrast, embryos defective for Cdk4 and Cdk6 die during the late stages of embryonic development because of severe anemia." (PMID 31430272, 2019). "Similarly, MEFs isolated from Cdk4/6 double knock-out embryos proliferate in vitro with only slight defects in S phase, yet the embryos die in utero due to anemia." (PMID 36051751, 2022). "Anemia and thrombocytopenia are also commonly seen in patients treated with CDK4 inhibitors without increases in bleeding or transfusion requirements." (PMID 36051751, 2022). "Experiments with gene-deficient mice for CDK4 or CDK6 are viable, then lacking CDK4 and CDK6 die of severe anemia and hematopoietic abnormalities." (PMID 28193906, 2017).
esophageal cancer (23 papers, 2016 to 2025). A primary or metastatic malignant neoplasm involving the esophagus. "Pyrotinib treatment reduced the cyclin D1 and cyclin-dependent kinase 4 (CDK4) levels for increasing G0/G1 arrest, resulting in the enhanced anti-proliferation effects of radiotherapy in esophageal cancer cells." (PMID 39193330, 2024). "RBBP7 was identified and experimentally verified to be directly targeted by HIF1α to up-regulated CDK4 in hypoxia conditions to promote viability, proliferation, and stemness of esophageal cancer cells." (PMID 35538026, 2022). "We conclude that hypoxia induces high expression of RBBP7 which is at least partially mediated by HIF1α, up-regulates the expression of downstream CDK4, and thereby promotes tumor progression in esophageal cancer cells." (PMID 35538026, 2022). "Second, the activation of CXCR2 results in increased expression of early growth response-1 (EGR-1) in esophageal cancer, which increases proliferation by elevating the expression of cyclin-dependent kinase 4 (CDK4)." (PMID 35216283, 2022). "Hypoxia-induced HIF1α up-regulates RBBP7 expression, which promotes esophagus cancer cell viability, proliferation, and stemness with increased cyclin-dependent kinase 4 (CDK4) expression." (PMID 35538026, 2022). "In summary, our investigation demonstrates that the hypoxia microenvironment can induce HIF1α-dependent RBBP7-mediated up-regulation of CDK4 to promote the progression of esophageal cancer." (PMID 35538026, 2022). "Conversely, miR-486 was found to suppress the growth and metastasis of esophageal cancer by targeting CDK4/BCAS2." (PMID 31976317, 2019). "CDK4 silencing or PD0332991 treatment significantly inhibits the proliferation of esophageal cancer cells." (PMID 31358010, 2019). "Mechanistic analysis revealed that hypoxia-induced HIF1α could up-regulate RBBP7 to promote the expression of downstream CDK4, thereby enabling the tumor progression of esophageal cancer cells." (PMID 35538026, 2022). "Some studies have verified that CDK4 is usually overexpressed and/or over-actived in human esophageal cancer, which can regulate the G1-S phase of the cell cycle by inactivating the tumor-suppressive retinoblastoma protein (Rb) in cancer cells and dividing cells." (PMID 35538026, 2022). "Hypoxia-induced HIF1α could up-regulate RBBP7/CDK4 to promote esophageal cancer progression, which might be considered as a treatment option." (PMID 35538026, 2022). "Further results showed that RBBP7 and CDK4 exhibit a significant positive correlation in esophageal cancer patients (r=0.3155,P<0.0001), indicating that RBBP7 might regulate the expression of CDK4." (PMID 35538026, 2022). "Consistently, we found that pyrotinib could reduce cyclin D1 and CDK4 levels in esophageal cancer cells." (PMID 32022229, 2020). "In conclusion, based upon our date, we found that pristimerin could induce the downregulation of cyclin E, CDK2, and CDK4 to lead to the block of G0/G1 transition, which gave rise to cell death in esophageal cancer." (PMID 31218209, 2019). "miR-124 expression was reduced in esophageal cancer tissue, and miR-124 overexpression could increase the percentage of apoptotic cells following radiotherapy by targeting CDK4 in esophageal cancer TE-1 cells." (PMID 28388588, 2017). "The miR-124/CDK4 axis was an important mechanism in regulating the radiation sensitivity of human esophageal cancer cells, and targeting CDK4 may improve the clinical efficacy of radiotherapy." (PMID 28388588, 2017). "In esophageal cancer, dysregulation of the FBXO4-cyclin D1-RB axis promotes glutamine addiction and highlights a therapeutic weakness for overcoming CDK4/6 inhibitor resistance." (PMID 35877430, 2022).
esophageal cancer (continued). "For example, approximately 45% of driver events in esophageal cancer included focal amplifications in cell cycle genes such as CCND1/2/3 and CDK4/6/9, in addition to amplifications in ERBB2, KRAS, MYC." (PMID 33889297, 2021). "CDK1/2 overexpression has been reported in CRC and esophageal cancers, CDK4 overexpression has been described in most types of GI tumors and CDK6 overexpression has been observed in CRC and esophageal cancers." (PMID 34503239, 2021). "For esophageal cancer, the GeneCards database ranks CDK4 (cyclin-dependent kinase 4), DNMT3B (DNA methyltransferase 3 beta), and MAGEA4 (MAGE family member A4) as the top three relevant genes." (PMID 33273919, 2020). "Trilaciclib, a novel CDK4/6 inhibitor with myeloprotective effects, has not yet been evaluated for its use in esophageal cancer treatment." (PMID 40232146, 2025).
astrocytomas (21 papers, 2013 to 2025). "Meanwhile, other molecular biomarkers indicating worse outcome in IDH‐mutant astrocytoma, including NOTCH1 mutations and incomplete resections in oligocytoma and PIK3R1 mutations, RB1 mutations and CDK4 mutations and amplifications in astrocytoma." (PMID 37667984, 2023). "Relatedly, CDK4 amplification has been associated with poor outcomes in astrocytomas." (PMID 36147920, 2022). "Another study demonstrated that combination of CDK4 amplification and/or CDKN2A deletion, and chromosome 14 loss conferred poor prognosis in astrocytoma, IDH-mutant." (PMID 38012788, 2023). "Although the overall prognostic significance is still controversial, a large-scale study demonstrated that in addition to CDKN2A/B deletion, CDK4 amplification, which also deregulates Rb pathway, was associated with poor prognosis in IDH-mutant astrocytoma." (PMID 38012788, 2023). "V12Ha-Ras transgenic mice under the control of the GFAP promoter form astrocytomas that have the added genetic complexity of the aberrant expression of p16, p19, and PTEN while overexpressing EGFR, MDM2, and CDK4, with chromosomal rearrangements comparable to human astrocytomas." (PMID 41154198, 2025). "Also, combined therapy with BRAFV600E and CDK4/6 inhibitors was effective to prolong survival in mouse models for astrocytoma." (PMID 29156680, 2017). "Consistent with parent recurrent tumor cells, amplifications of CDK4 and MDM2 and PDGFRA gain were found, while CDKN2A/B was identified as homozygous deletion in the xenografts, qualifying for integrated diagnosis of astrocytoma, IDH2-mutant, CNS WHO grade 4." (PMID 38012788, 2023). "In IDH1-mutant astrocytoma cases with available clinical and CNA data (total 161 cases), we found that tumors harboring either CDKN2A deletion, PDGFRA amplification, CDK4 amplification, or MDM2 amplification conferred poor prognosis in these cohorts." (PMID 38012788, 2023). "Consistent with YMG25R parent tumor cells, gain of PDGFRA and amplification of CDK4 and MDM2 were observed, while CDKN2A HD was identified in the xenografts, qualifying for astrocytoma, IDH-mutant, CNS WHO grade 4 according to the WHO CNS5 criteria." (PMID 38012788, 2023). "To verify if IDH1/2-mutant astrocytomas with CDKN2A, PDGFRA, CDK4, or MDM2 CNA promotes poor prognosis, we used the GLASS and MSK diffuse glioma datasets (total 1,448 cases)." (PMID 38012788, 2023). "that used FISH to examine CDKN2A, CDK4, and PDGFRA copy number alterations in grade 2 and 3 astrocytomas." (PMID 33081848, 2020). "Of note, we found that CDK4/6 inhibitor selectively suppressed cell viability of phospho-Rb-upregulated, recurrent cells, further supporting the critical role of cell cycle deregulation in progression in IDH2-mutant astrocytoma." (PMID 38012788, 2023). "In the present study, we subclassify 135 astrocytomas (67 IDH-wildtype and 68 IDH-mutant) from The Cancer Genome Atlas dataset (TCGA) on the basis of grade, IDH-status, and the previously established prognostic factors, CDK4 amplification and CDKN2A/B deletion, within the IDH-mutant groups." (PMID 31177992, 2019). "IDH-mutant astrocytomas with either CDK4 amplifications or CDKN2A deletions had significantly shorter survival (median PFS of 32 months; median OS of 36 months) compared to IDH-mutant astrocytomas without these alterations (median PFS of 95 months, p = 0.02; median OS of >172 months, p = 0.02)." (PMID 32640746, 2020).
cutaneous melanoma (21 papers, 2005 to 2025). A primary melanoma arising from atypical melanocytes in the skin. "In patients with non-cutaneous melanoma, genetic aberrations in the cyclin-dependent kinase 4 (CDK4) pathway were shown to be associated with innate resistance to PD-1 blockade." (PMID 37056769, 2023). "Based on the GenoMEL centers’ study that involved 2137 cutaneous melanoma patients originating from 466 families with at least 3 cutaneous melanoma cases per family, the frequency of the CDK4 mutations is 2-3%." (PMID 35465855, 2022). "After excluding patients positive for CDKN2A/CDK4 pathogenic variants and those affected by non-cutaneous melanomas, our study cohort comprised 984 cutaneous melanoma patients, 22 MITF+ and 962 MITF−." (PMID 32054529, 2020). "AM also has different oncogenic drivers from cutaneous melanoma, including inconstant KIT mutation rates (3–29%), CCND1 and CDK4 amplification, and deletion or mutations in different genes, such as CDK2NA, PTEN, NF1, and hTERT." (PMID 33344255, 2020). "AM has different oncogenic drivers from the cutaneous melanoma, including fewer BRAF mutations (10–23%), inconstant KIT mutation rates (3–29%), CCND1 and CDK4 amplification, and deletion or mutations in different genes, such as CDK2NA, PTEN, NF1, and hTERT." (PMID 33344255, 2020). "We have previously shown that keratinocytic RXRα has a role in acute UV-induced melanocyte proliferation, in chemically induced melanomagenesis and in cutaneous melanoma formation when combined with mutant Cdk4 by chemical carcinogenesis." (PMID 29121869, 2017). "However, the genetic alterations that give rise to uveal melanoma (i.e., GNAQ) differ from those in cutaneous melanoma (i.e., BRAF, CDKN2A, CDK4), suggesting that different pathways may be involved in their progression." (PMID 35525274, 2022).